CD163 (CD163 molecule)
Diseases named in the same sentence as CD163 in open-access papers (continued):
Sharing a sentence is not in itself a finding about the gene and the disease.
meningoencephalitis (1 paper, 2018). Inflammation of the meninges and brain, generally secondary to an infectious cause. "In contrast, CD163 expression was increased in cases with symptoms of meningoencephalitis, accompanied by intense vascular proliferation and focal necrosis in the cortical layer." (PMID 29311619, 2018).
metastatic cancer (1 paper, 2021). A carcinoma which has spread from the original site of growth to another anatomic site. "Myeloid features and markers (CD163, CD33, CD68 etc.)can be seen in metastatic cancer cells." (PMID 34257573, 2021).
microcytic anemia (1 paper, 2020). Anemia in which the red blood cell volume is decreased. "Macrophages, especially their CD163+ fraction, are responsible for proper iron redistribution, and their deficiency is a primary cause of microcytic anemia in HO‐1−/− mice." (PMID 31885181, 2020).
muscular dystrophy (1 paper, 2024). Muscular dystrophy (MD) refers to a group of more than 30 genetic diseases characterized by progressive weakness and degeneration of the skeletal muscles that control movement. "For instance, pediatric patients suffering from muscular dystrophy evidenced augmented CD163 expression in monocytes upon G-CSF stimulation, signaling the cytokine’s propensity to favor monocyte skewing towards an M2 macrophage phenotype." (PMID 38967628, 2024).
myasthenia (1 paper, 2024). "In different clusters, symptom duration, severe myasthenia, cardiac involvement, serum inflammatory marker levels (ESR, CRP, C4), and CD163+ macrophage distribution were confirmed as discriminators." (PMID 38651547, 2024).
myelodysplastic syndrome (1 paper, 2024). A clonal hematopoietic disorder characterized by dysplasia and ineffective hematopoiesis in one or more of the hematopoietic cell lines. "Recently, we identified polyploid giant cells expressing CD61, Syncytin-1, telomerase, Runx2, and macrophage markers (CD11b, CD68, and CD163) in the circulation of patients with myelodysplastic syndromes (MDS)." (PMID 38611120, 2024).
nasal natural killer/T cell lymphoma (1 paper, 2014). "Moreover, monocytes were shown to induce proliferation and LMP1 expression in cells of EBV-associated nasal natural killer/T cell lymphoma and a correlation of serum CD163 and plasma EBV-DNA in cHL was reported." (PMID 25470820, 2014).
neutropenia (1 paper, 2023). A decrease in the number of neutrophils found in the blood. "Within PGF samples, CD163 expression was increased compared to GGF samples (adj P = 0.007), suggesting skewing of monocyte/macrophage populations, with decreased CD66b reflecting the neutropenia of PGF (adj p = 9.89E−06)." (PMID 37818364, 2023).
nosocomial infection (1 paper, 2015). An infection acquired in a hospital or other healthcare setting. "The remaining transcriptomic candidates of the heme degradation pathway (HP, CD163, HMOX1; IL-10) and IL-8 clustered together, with moderate correlation to nosocomial infections (lower half of the heatmap)." (PMID 26607226, 2015).
orchitis (1 paper, 2020). Inflammation of one or both testes due to viral or bacterial infections. "Here, the number of TM subsets CD68+CD163- and (CD68+CD163+) increases progressively from the end of the immunization period to the severe orchitis stage, with minor changes in the number of resident CD163+ TM." (PMID 33101311, 2020).
osteomyelitis (1 paper, 2020). An acute or chronic inflammation of the bone and its structures due to infection with pyogenic bacteria. "Here, we show that an anti-IsdB mAb can facilitate S. aureus internalization and survival in macrophages in vitro and mediate S. aureus dissemination in a murine model of implant-associated osteomyelitis via a multimolecular complex that includes Spa, the anti-IsdB mAb, IsdB, Hb-Hp, and CD163." (PMID 33004694, 2020).
papillary thyroid carcinoma (1 paper, 2025). "Although the Medians of CD68+ and CD163+ cells in the TC group were almost similar, the balance of M1 and M2 macrophages varied significantly inside the group, so the CD68/CD163 ratio was low in patients with papillary thyroid carcinoma, comprising 0.563 (0.082–3.0)." (PMID 39936166, 2025).
paraganglioma (1 paper, 2024). A benign or malignant neoplasm arising from paraganglia located along the sympathetic or parasympathetic nerves. "The presence of CD163 and CD68 positive macrophages in pheochromocytoma and extra adrenal abdominal paragangliomas has been reported previously." (PMID 39619326, 2024).
Peptic ulcer (1 paper, 2023). The term peptic ulcer refers to acid peptic injury of the digestive tract, resulting in mucosal break reaching the submucosa. "Related studies have found that CD163 and CD14 are increased in H. pylori infection, especially in patients with peptic ulcers." (PMID 36973348, 2023).
Peri-Implantitis (1 paper, 2022). An inflammatory process with loss of supporting bone in the tissues surrounding functioning DENTAL IMPLANTS. "A borderline significance (p = 0.054) was observed when the CD80/CD163 ratio was compared between peri-implantitis and healthy peri-implant tissue samples, the latter being lower." (PMID 36286036, 2022). "Peri-implantitis lesions showed a tendency towards a higher CD80/CD163 ratio than in healthy peri-implant mucosa with a borderline difference (p = 0.054)." (PMID 36286036, 2022). "CD80/CD163 or CD80/CD206 positive cell ratios have been used to immunohistochemically assess macrophage polarization in various conditions such as colorectal cancer, arthritis, aging, lung injury and peri-implantitis." (PMID 36286036, 2022). "The CD80/CD163 ratio was also decreased in the peri-implantitis group but without a statistically significant difference." (PMID 36286036, 2022).
periampullary adenocarcinoma (1 paper, 2017). An adenocarcinoma that arises from the periampullary region. "This study is, to our best knowledge, the first to investigate the prognostic role of tumour-infiltrating CD1a+, CD68+ and CD163+ and MARCO+ immune cells in periampullary adenocarcinoma, with particular reference to morphological type." (PMID 28673320, 2017).
pericarditis (1 paper, 2023). An inflammatory process affecting the pericardium. "Interestingly, sterile pericarditis also increased the number of pro-healing antiinflammatory M2 macrophages (CD163-expressing) by 1.8-fold ± 0.5-fold from sham (P < 0.01)." (PMID 37384420, 2023).
pituitary adenomas (1 paper, 2024). "In addition, the ratio of the M2 marker CD163 to the M1 marker HLA‐DR was about three times higher in pituitary adenomas than in normal pituitary tissue, indicating a higher proportion of M2‐type macrophages in pituitary adenomas." (PMID 38738958, 2024).
Pleuritis (1 paper, 2022). Inflammation of the pleura. "The FIHC data supports the flow cytometry data which showed a similar elevation in CD163+CD206- subpopulation at necropsy, without a difference between animals that developed pleuritis." (PMID 35789343, 2022).
proliferative glomerulonephritis (1 paper, 2024). A constellation of renal disorders characterized by an increase number of cells in the glomerulus; these disorders generally present with nephrotic syndrome, and generally progress to end stage renal failure over a matter of weeks to years, depending on the etiology. "In cases of proliferative glomerulonephritis and acute tubulointerstitial nephritis, CD163 + M2 macrophages were found to be the most abundant subtype in both the glomerular and interstitial compartments." (PMID 38740765, 2024).
Rb (1 paper, 2022). "Immune-related genes such as CD86, CD19, and CD36 were significantly upregulated in advanced Rb while displaying a low degree of expression of CD81 and CD163." (PMID 35626705, 2022).
rhinitis (1 paper, 2022). An inflammation of the mucous membrane lining the nose, usually associated with nasal discharge. "Indeed, FGF2 and CD163 were significantly expressed in NPC tissues compared with rhinitis tissues." (PMID 35439170, 2022).
salivary gland cancer (1 paper, 2023). A primary or metastatic malignant neoplasm that affects the major or minor salivary glands. "A selected number of immunohistochemical markers related to TILs (CD3, CD4, CD68, and FOXP3) and TAMs (CD68 and CD163) were investigated on major salivary gland cancers." (PMID 37465638, 2023).
sarcomatoid carcinoma (1 paper, 2018). A malignant epithelial neoplasm characterized by the presence of spindle cells and anaplastic morphologic features. "As other immunohistochemical markers were negative, including CD45, CD163, CD68, Desmin, Myogenin, Melanoma, S100, α-SMA, Cytokeratin 7, Cytokeratin 20, MDM2 and CDK4, the tumors were diagnosed as sarcomatoid carcinomas." (PMID 29874846, 2018).
SARS-CoV infection (1 paper, 2022). "Increased CD163 positive macrophages gathering around virus positive cells were recently shown also in a macaque model of SARS-CoV infection, indicating that infected pneumocytes may lead to macrophage recruitment in coronavirus infections." (PMID 35992303, 2022).
Seizure (1 paper, 2020). A seizure is an intermittent abnormality of nervous system physiology characterized by a transient occurrence of signs and/or symptoms due to abnormal excessive or synchronous neuronal activity in the brain. "To determine whether tissue injury or macrophage-related inflammation is associated with the GCD phenotypes, we examined the hippocampal expression of injury markers GFAP and CD163 in 6 seizure patients and 10 controls." (PMID 32317027, 2020).
seminoma (1 paper, 2025). A radiosensitive malignant germ cell tumor found in the testis (especially undescended), and extragonadal sites (anterior mediastinum and pineal gland). "This study is the first to quantitatively and phenotypically characterize CD68+ and CD163+ tumor-associated macrophages (TAMs) in N0-stage seminomas at pT1 and pT2 stages." (PMID 40843751, 2025). "Comparative immunohistochemical analysis of CD68+ and CD163+ TAMs between pT1- and pT2-stage seminomas revealed pronounced interindividual variability, as reflected by the interquartile range (Q1–Q3) and visualized in the violin plot." (PMID 40843751, 2025). "CD163+ TAMs exhibited an even more pronounced increase: their median values in pT1- and pT2-stage seminoma exceeded those in the control group by about 23 and 79 times, respectively." (PMID 40843751, 2025). "This study aimed to quantitatively and phenotypically characterize CD68+ and CD163+ TAMs in non-metastatic seminomas (pT1N0M0 and pT2N0M0)." (PMID 40843751, 2025). "The aim of the present study was to compare the quantity and spatial distribution of TAMs (CD68+/CD163+) in non-metastatic seminoma at the pT1 and pT2 stages in order to assess their potential association with tumor progression." (PMID 40843751, 2025). "In contrast, our study includes a substantially larger cohort of patients with non-metastatic seminoma and, for the first time, provides a comprehensive quantitative and phenotypic analysis of TAMs (CD68+/CD163+), including their spatial distribution across pT1 and pT2 stages." (PMID 40843751, 2025).
small cell lung carcinoma (1 paper, 2023). Small cell lung cancer (SCLC) is a highly aggressive malignant neoplasm, accounting for 10-15% of lung cancer cases, characterized byrapid growth, and early metastasis. "CD163 was a marker of M2-macrophage and an elevated level of CD163 is associated with poor prognosis in patients with small cell lung cancer." (PMID 38223688, 2023).
squamous cell carcinoma of the skin (1 paper, 2015). "Specifically, studies on squamous cell carcinoma of the skin have reported that CD163+ macrophages can produce both M1 and M2 macrophage-related proteins." (PMID 26568320, 2015).
systemic vasculitis (1 paper, 2021). "The results showed that urine CD163 was effective in differentiating systemic vasculitis with an area under the ROC curve of 0.738." (PMID 33997033, 2021). "When grouped according to different pathological mechanisms, we unexpectedly found that CD163 levels were significantly higher in granulomatous vasculitis than in necrotizing vasculitis." (PMID 33997033, 2021). "This study is aimed at evaluating the CD163 levels in relation to systemic vasculitis and renal involvements." (PMID 33997033, 2021). "Urinary CD163 levels were significantly higher in patients with systemic vasculitis, especially in patients with renal involvement." (PMID 33997033, 2021). "After control factors age, sex, and BMI, urinary CD163 levels in systemic vasculitis patients were positively correlated with serum creatinine, blood urea nitrogen, and β-2 microglobulin (r = 0.45, 0.48, and 0.46; p = 0.001, 0.001, and 0.002, respectively)." (PMID 33997033, 2021). "Thus, urinary CD163 has the potential to be a biomarker for systemic vasculitis with renal involvement." (PMID 33997033, 2021). "Interestingly, the level of urinary CD163 in granulomatous vasculitis [median 86.95, IQ (41.99 and 184.82)] was significantly higher than that in necrotizing vasculitis [median 45.73, IQ (21.43 and 74.43)], p = 0.016." (PMID 33997033, 2021). "In addition, we found the level of urinary CD163 in granulomatous vasculitis (including TA, GPA, and EGPA) was significantly higher than that in necrotizing vasculitis (including PAN) [86.95 (41.99 and 184.82) pg/ml] vs. [45.73 (21.43 and 74.43) pg/ml, p = 0.016]." (PMID 33997033, 2021). "Furthermore, systemic vasculitis patients with renal involvement had significantly higher urinary CD163 levels relative to patients without renal involvement [86.95 (47.61 and 192.38) pg/ml] vs. [41.99 (17.70 and 71.95) pg/ml, p = 0.005]." (PMID 33997033, 2021).
tendinopathy (1 paper, 2022). "We identified S100A8 immunopositive staining which colocalized with the macrophage marker CD163 in early-stage tendinopathy." (PMID 38655164, 2022).
thoracic cancer (1 paper, 2025). A primary or metastatic malignant neoplasm affecting the tissues of the thorax. "When monocytes were co-cultured with A549, we reproduced the heightened CD163 expression as seen with other thoracic cancer cell lines." (PMID 41310721, 2025).
tongue cancer (1 paper, 2021). A malignant neoplasm affecting the tongue. "Tongue cancer cell-derived CCL20 that was induced by interaction with macrophages promotes CD163 expression on macrophages." (PMID 34178651, 2021).
tubulointerstitial nephritis (1 paper, 2025). "Although in vitro studies indicate that M1-polarized macrophages express higher levels of 1α-hydroxylase than M2 macrophages, the in vivo microenvironment of IgG4-related tubulointerstitial nephritis is dominated by CD163+ M2-like macrophages, within which 1α-hydroxylase was observed to co-localize." (PMID 41451224, 2025).
tularemia (1 paper, 2012). Tularemia is an infection caused by the bacterium Francisella tularensis. "In the early phase of tularemia, numerous neutrophils, monocytoid B cells (MBLs), histiocytic cells, T cells, S-100+, Langerin+, CD83+, CD163+ dendritic cells are found in lesions." (PMID 22588497, 2012).
urothelial cell carcinoma (1 paper, 2021). "Another study suggested that high CD163 expression indicated a poor prognosis of patients with urothelial cell carcinoma." (PMID 34395626, 2021).
uveitis (1 paper, 2018). An inflammatory process affecting a part of or the entire uvea. "IAU patients showed a transiently increased frequency of CD56- and CD163-positive monocytes and of both granulocytic myeloid-derived suppressor cells and Th17 cells during active uveitis." (PMID 30105034, 2018). "Within the IAU group, classical monocytes showed increased CD56 and CD163 expression during uveitis activity." (PMID 30105034, 2018). "Therefore, the increased frequency of IL-17+ T cells during active uveitis observed in IAU patients might contribute to the elevation of CD163+ monocytes in this cohort." (PMID 30105034, 2018). "Furthermore, CD163+ monocytes were increased in IAU patients during uveitis activity." (PMID 30105034, 2018). "Taken together, the elevated frequency of CD56+ and CD163+ monocytes, granulocytic MDSC, and Th17 cells during uveitis activity represents unique features in IAU patients, suggesting a Th17-driven immune response in comparison with HLA-B27-associated AAU patients." (PMID 30105034, 2018).
Varicose veins (1 paper, 2024). Enlarged and tortuous veins. "A total of 47 patients’ (39 with PAD and 8 with varicose veins) samples of sartorius muscle were analysed with immunohistology for CD45+ leucocytes, while 40 samples were analysed for CD163 macrophages (39 with PAD and 8 with varicose veins)." (PMID 38667739, 2024).
vascular dementia (1 paper, 2023). A degenerative vascular disorder affecting the brain. "Moreover, the relative percentage of CD163 was significantly higher in Alzheimer’s patients than in those patients with vascular dementia (MFI 93.6 vs. MFI 84.9, p = 0.036)." (PMID 37445910, 2023).
Vestibular schwannoma (1 paper, 2021). A vestibular schwannoma (also known as acoustic neuroma, acoustic neurinoma, or acoustic neurilemoma) is a benign, usually slow-growing tumor that develops from the VIIIth cranial nerve supplying the inner ear. "The authors investigated the role of tumor-associated macrophages in vestibular schwannomas by analyzing the expression of CD163, M-CSF and IL-34 in ten fast- and slow-growing vestibular schwannomas." (PMID 33530441, 2021). "Thus, a higher expression score of CD3, CD8, CD68 and CD163 was associated with larger preoperative tumor size and faster volumetric growth in vestibular schwannomas." (PMID 33530441, 2021). "To further define the impact of inflammation with tumor growth in vestibular schwannoma, we performed immunohistochemical analyses of CD3, CD8, CD68 and CD163 to assess lymphocyte and macrophage infiltration in 923 tumor tissue samples of surgically resected vestibular schwannomas." (PMID 33530441, 2021).
Whipple disease (1 paper, 2015). A systemic infection caused by the Gram-positive bacterium Tropheryma whipplei. "Interestingly, in Whipple’s disease, Tropheryma Whipplei accumulate in duodenal macrophages which express a similar phenotype to the E. coli-laden macrophages in this study (high IL-10, CD163) which is thought to facilitate their persistence." (PMID 26137941, 2015).
xanthoma (1 paper, 2025). A non-neoplastic disorder characterized by a localized collection of histiocytes containing lipid. "These xanthoma cells contain plenty of lipids, and CD68, CD163, and CD63 are positive in immunohistochemistry, indicating a macrophage phenotype." (PMID 40502883, 2025).